SOX9 (SRY-box transcription factor 9)
Diseases named in the same sentence as SOX9 in open-access papers (continued):
Sharing a sentence is not in itself a finding about the gene and the disease.
campomelic dysplasia (continued). "It should be pointed out that canine XX DSD affects only the reproductive system, and no cases were identified with skeletal dysplasia, which has been observed in some human syndromes with SOX9 mutations, such as acampomelic campomelic dysplasia and Pierre Robin sequence." (PMID 31220175, 2019). "Our model suggests for the first time, the modulation of a gene other than Sox9 that is capable of recapitulating a large subset of pathologies associated with campomelic dysplasia, which may be exploited for future therapeutic intervention." (PMID 28166224, 2017). "Heterozygous mutations in and around Sox9 were shown to cause campomelic dysplasia, a severe form of human chondrodysplasia often accompanied by male sex reversal and defects in other nonskeletal organs, highlighting its critical role in chondrogenesis and other tissues." (PMID 28630873, 2017). "Campomelic dysplasia results from de novo heterozygous SOX9 mutations." (PMID 28546996, 2017). "It is not very suitable for detection of duplications and deletions, especially in extra-genic regions, such as the SOX9 control regions that may cause campomelic dysplasia when deleted." (PMID 26380986, 2015). "Furthermore, heterozygous mutations in Sox9 in both mice and humans, result in campomelic dysplasia, a syndrome associated with dwarfism, skeletal malformations, cleft palate, XY sex reversal and often hermaphroditism." (PMID 25629959, 2015). "Campomelic dysplasia is a skeletal malformation syndrome caused by mutations in SOX9." (PMID 24731683, 2014). "SOX9 has multiple functions other than testis differentiation: expression is noted at sites of chondrogenesis in mouse embryo, and heterozygous mutation is associated with the bone dysmorphology syndrome, campomelic dysplasia (CD)." (PMID 25265165, 2014). "Mutations in the coding region of SOX9 cause campomelic dysplasia (CD)." (PMID 23648064, 2013). "Hoxa4 may have a role in vertebral development in mice, while mutations in the human SOX9 gene have been found to cause campomelic dysplasia, a disease characterised by shortness and bowing of long tubular bones, hypoplastic scapulae and narrow iliac wings." (PMID 24176111, 2013). "Mutations in the SOX9 gene may result in autosomal XY sex reversal and in campomelic dysplasia, a syndrome with severely malformed skeleton." (PMID 22515642, 2012). "In humans, Sox9-haploinsufficiency is associated with the syndrome campomelic dysplasia (CD)." (PMID 21829703, 2011). "Mutations in SOX9 have been correlated to a campomelic dysplasia with skeletal anomalies." (PMID 21176156, 2010). "Furthermore, SOX9 is expressed in presumptive cartilage during embryo development, and mutations in the human SOX9 gene, which result in haploinsufficiency of SOX9, cause campomelic dysplasia with skeletal malformation and dwarfism." (PMID 17935617, 2007). "Furthermore, sox9a mutant zebrafish embryos exhibit craniofacial and cartilage developmental defects analogous to human campomelic dysplasia, which is caused by SOX9 haploinsufficiency, highlighting the conservation of SOX9 function across vertebrate facial formation." (PMID 41208708, 2025). "Similarly, variants of SOX9 also cause campomelic dysplasia characterized by severe short stature." (PMID 35571680, 2022). "Mutations have been identified in SOX9 that cause haploinsufficiency and result in the human clinical condition campomelic dysplasia (CMD1)." (PMID 21176156, 2010). "The dysregulation of Sox9 during chondrogenesis leads to a skeletal malformation termed campomelic dysplasia and has emerged as a significant factor in various other human diseases, including cancer." (PMID 42193997, 2026). "The role of Sox9 in RS is known by its direct involvement in campomelic dwarfism (severe osteodystrophy—RS—sexual ambiguity) and by the involvement of mutations in regulatory regions upstream of Sox9 in familial forms of isolated RS." (PMID 40474278, 2025).
campomelic dysplasia (continued). "SOX-9 haploinsufficiency in humans results in campomelic dysplasia, a lethal skeletal malformation syndrome and XY sex reversal." (PMID 40004707, 2025). "46,XY, campomelic dysplasia cell line: 46, XY;CD-derived 6TF SLCs showed increased SOX9 expression; over the respective GFP control which was notably much smaller than that observed in control 46, XY-derived SLCs." (PMID 38520033, 2024). "In humans, haplo-insufficiency of SOX9 results in campomelic dysplasia (CD), a human syndrome characterized by defective chondrogenesis and sex reversal." (PMID 38238288, 2024). "A previous study reported acampomelic campomelic dysplasia (ACD) and campomelic dysplasia (CD) mouse models in which the CRISPR/Cas9 system was used to knock out the SOX9 gene, a transcription factor involved in the development of cartilage." (PMID 36833410, 2023). "The role of SOX9 in testis formation and sex determination was first recognized in patients with campomelic dysplasia, of whom around 75% with a 46, XY male karyotype bearing one mutant SOX gene exhibit male-to-female sex reversal." (PMID 35805171, 2022). "Sox9 perturbation is involved in campomelic dysplasia (CD), as Sox9 also has a key role in chondrogenesis." (PMID 36430529, 2022). "An atypical form of CMPD, known as acampomelic campomelic dysplasia occurs as a result of alterations between 50–375 kb upstream of SOX9 resulting in a phenotype similar to that of CMPD but with the absence of bowed limbs." (PMID 33810596, 2021). "Heterozygous loss-of-function mutations occur within either the coding or regulatory region for SOX9 in patients with Campomelic Dysplasia (CMPD; OMIM 114290)." (PMID 33810596, 2021). "The transcription factor Sox9 was first investigated in the context of campomelic dysplasia (CD), a disease related to defective chondrogenesis and XY sex reversal." (PMID 34112251, 2021). "Previous work showed that heterozygous deletion of Sox9 recapitulates many aspects of campomelic dysplasia." (PMID 32991838, 2020). "The SNP rs2193054 in the SOX9 locus is located at the proximal break point cluster region of campomelic dysplasia (CMPD [MIM 114290])." (PMID 29921221, 2018). "WDR35 and SOX9 were related to known craniofacial malformations, i.e., cranioectodermal dysplasia 2 and campomelic dysplasia, respectively." (PMID 29921221, 2018). "Sox9 was previously shown to bind to pairs of inverted Sox motifs from studies done on campomelic dysplasia patients and in cell culture." (PMID 28630873, 2017). "To date, mutations within the coding region and translocations around the SOX9 gene both constitute the majority of genetic lesions underpinning human campomelic dysplasia (CD)." (PMID 28166224, 2017). "Mouse studies show that haploinsuffiency produces a skeletal phenotype similar to campomelic dysplasia in that Sox9+/- mice show hypoplastic scapulae and thin pubic bones." (PMID 27622494, 2016). "For example, SOX9 has been shown to be involved with campomelic dysplasia, a syndrome which, among other symptoms, is characterized by vertebrae malformation and a smaller number of ribs." (PMID 26830357, 2016). "For example, SOX9 dimerization mutants have been identified in some campomelic dysplasia patients, suggesting the importance of the repetition of the sequence." (PMID 26040697, 2015). "In a mouse model that phenocopies the generalized cartilage hypoplasia of campomelic dysplasia, hypertrophic chondrocyte differentiation is accelerated, suggesting that SOX9 has a role in this differentiation step." (PMID 25229425, 2014). "Chromosomal rearrangements can remove one or more cis-regulatory elements of the SOX9 gene, leading to campomelic dysplasia." (PMID 23284961, 2012). "In vivo, mice with reduced Sox9 function fail to develop cartilage and mimic the human skeletal disorder, Campomelic Dysplasia, further supporting a positive role for Sox9 in promoting formation of cartilaginous connective tissue." (PMID 22046352, 2011).
campomelic dysplasia (continued). "These genes are associated with recognizable syndromes such as (acampomelic) campomelic dysplasia (SOX9), cerebro‐costo‐mandibular syndrome (SNRPB), SATB2‐associated syndrome (Glass syndrome, SATB2), Catel‐Manzke syndrome (TGDS), TARP syndrome (RBM10), and Stickler syndrome (COL2A1, COL11A1)." (PMID 41077824, 2026). "For instance, dimerization-deficient SOX9 results in a milder form of Campomelic dysplasia without causing sex reversal." (PMID 39936824, 2025). "Notably, we also identified significant variants in the causative genes of rare neurodevelopmental disorders sharing comorbidities with FASD, including STRA6 (Matthew–Wood), SOX9 (Campomelic Dysplasia), FDG1 (Aarskog), and 22q11.2 deletion syndrome (TBX1)." (PMID 38785976, 2024). "Inversion prone position effects are not only limited to other species, it has also been reported in some human disease conditions, such as aniridia (PAX6), campomelic dysplasia (SOX9), familial adenomatous polyposis (APC) and Saethre-Chotzen syndrome (TWIST1)." (PMID 31191618, 2019). "Chondrocytes cannot form in Sox9 null mutants and heterozygous mutations in SOX9 severely disrupt skeletal development, causing campomelic dysplasia." (PMID 29659575, 2018). "These included regulator of G-protein signaling 4 (RGS4) and 7 (RGS7), which were both upregulated by CCG-1423, and CTGF (connective tissue growth factor), and SOX9 (sex determining region Y-box 9, also referred to as campomelic dysplasia, autosomal sex reversal) which were down-regulated." (PMID 27600078, 2016). "While Sox9 gene haplo-insufficiency can lead to genetic skeletal disorders like campomelic dysplasia (CMD) (OMIM#114290) characterized by bowing long bones." (PMID 32396528, 2020). "For example, the regulatory landscape of SOX9 was predicted to be disturbed by a translocation 721 kb upstream of the gene in individual P5, whose phenotype is mainly characterized by acampomelic campomelic dysplasia with Pierre-Robin syndrome (PRS) including a cleft palate." (PMID 31801603, 2019). "SOX9 haploinsufficiency underlies campomelic dysplasia (CD) with or without testicular dysgenesis." (PMID 26740947, 2015). "Finally, in agreement with our expression studies on human skin, humans carrying mutations in SOX9 display campomelic dysplasia affecting the skeleton and reproductive system but not melanocytes, whereas patients with mutations in SOX10 often exhibit pigmentary anomalies." (PMID 25629959, 2015). "In this respect, it is tempting to speculate on the classification of campomelic dysplasia (OMIM #114290), as links between Sox9 and genes involved in ribosomopathies were identified in the present work (SBDS, Rpl11, and Rps26)." (PMID 34235151, 2021). "SOX9 abnormalities lead to 46,XY gonadal dysgenesis with or without campomelic dysplasia." (PMID 26542297, 2015). "A role for SOX9 as transcriptional repressor of Col10a1 in non-hypertrophic chondrocytes is consistent with the observation that COL10A1 expression was up-regulated in cartilage isolated from SOX9 haploinsufficient campomelic dysplasia patients." (PMID 22072985, 2011). "Given the phenotypic overlap between craniofacial abnormalities of campomelic dysplasia and PRS, it had been long speculated, but not formally demonstrated, that regulatory elements harbored by the PRS region deletions might regulate SOX9." (PMID 32991838, 2020).
colorectal cancer (87 papers, 2006 to 2026). A primary or metastatic malignant neoplasm that affects the colon or rectum. "SOX9, an oncogene, is overexpressed in various malignancies, including lung, prostate, and colorectal cancers, and is also implicated in drug resistance across tumor types." (PMID 40843352, 2025). "This study shows loss of SOX9 function leads to increased invasion and metastasis in colorectal cancer via reduced epithelial differentiation and enhanced cancer stemness." (PMID 40179020, 2025). "Silencing the Sox9 expression in different colorectal cancer models resulted in a loss of clonogenic functions, together with reduced proliferation and the increased expression of intestinal differentiation markers." (PMID 37894295, 2023). "SOX9 inactivation is frequent in colorectal cancer (CRC) due to SOX9 gene mutations and/or to ectopic expression of MiniSOX9, a dominant negative inhibitor of SOX9." (PMID 27429045, 2016). "Loss-of-function mutations frequently observed in colorectal cancers (one frameshift indel in SOX9 and a nonsense mutation in FAM123B) were also found in ICC genomes." (PMID 27009864, 2016). "SOX9 is a transcription factor linked to stem cell maintenance and commonly overexpressed in solid cancers including colorectal cancer." (PMID 27571710, 2016). "Recently, exome sequencing has identified SOX9 as a recurrently mutated gene in colorectal carcinoma.." (PMID 27248473, 2016). "For instance, miR-613 is lowly expressed in colorectal cancer and has diagnostic and prognostic functions in colorectal cancer; miR-613 represses hepatocellular carcinoma cell dedifferentiation through the SOX9 signaling, which provides novel therapeutic targets for hepatocellular carcinoma." (PMID 36844868, 2023). "Expression of SOX9 enhances the invasion and migration of colorectal cancer cells, but this gene might be linked with invasion and migration of pituitary prolactinoma cellc." (PMID 33709028, 2021). "This dose-dependent effect of SOX9 is also implicated in colorectal cancer model in which a critical dose of SOX9 activity is essential for a maximum rate of proliferation while expression levels higher or lower than this dose would result in the reduction of cell growth." (PMID 30642390, 2019). "Moreover, SOX9 levels were shown recently to be inversely correlated with the risk of relapse in stage II colorectal carcinomas." (PMID 31275454, 2019). "Besides, Sox9 was also associated the carcinogenesis, development and prognosis of colorectal cancer, lung cancer, melanoma, hepatocellular carcinoma, skin tumors, and cervical cancer." (PMID 27589569, 2016). "SOX9 has been linked to clinical chemoresistance in colorectal cancer, an affect which may be partially mediated by EMT changes." (PMID 25975820, 2015). "Thus, mutations on SOX9 might impair the function of the protein encoded by SOX9, which might suppress the development of colorectal cancer." (PMID 37546388, 2023). "The observations that SOX9 inhibits the expression of oncogenes and stimulates the expression of tumour suppressor genes, together with the fact that it is frequently mutated in colorectal carcinomas and cell lines, suggest that SOX9 may play a tumour-suppressive role." (PMID 31275454, 2019). "However, whether SOX9 is oncogenic remains controversial as inactivating mutation of this gene is frequent in colorectal cancer." (PMID 28061475, 2017). "By contrast, both decreased SOX9 activity and oncogenic features of SOX9 have been implicated in colorectal carcinoma (CRC)." (PMID 27248473, 2016).
colorectal cancer (continued). "For example, a 3-mm TA harbored one of the highest MB of 6.45, with pathogenic mutational defects in numerous colorectal cancer driver genes (e.g., APC, SOX9, TCF7L2, ASXL1, ERBB3, MAP2K1, and PTPRS)." (PMID 40757636, 2025). "Because APC tumor suppressor defects in approximately 80% of colorectal cancers (CRCs) activate the Wnt/β-catenin pathway, we studied SOX9 inactivation in CRC biology." (PMID 40179020, 2025). "In sum, our findings suggest that a Wnt ligand, DKK2 is an upstream regulator of SOX9 expression for enhanced stem cell activity via the formation of LYZ+ cells with Paneth cell characteristics in colorectal cancers." (PMID 38659853, 2024). "Sox9 was previously reported as a driver of CSC functions in colorectal cancer through a genome-wide enhancer enrichment pattern promoting stem-like transcriptional programs." (PMID 37894295, 2023). "Here, we find using colony formation and cell growth assays that SOX9 surprisingly promotes the proliferation of Wnt-driven colorectal cancer (CRC) cells." (PMID 36423688, 2023). "Overexpression of SOX9 in an inducible SOX9 colorectal cancer cell model suppresses claudin 7 expression." (PMID 37998722, 2023). "Although primarily characterized as a repressor of Wnt/β-catenin target genes, correlative evidence hints at a more complex relationship between SOX9 and Wnt/β-catenin signaling in the intestinal epithelium and in colorectal cancer (CRC)." (PMID 36423688, 2023). "The inhibition pathway MALAT1/miR-145/SOX9 thus promotes colorectal cancer cell growth, migration, and invasion." (PMID 35887000, 2022). "SOX9 is overexpressed in hepatocellular, breast, bladder, gastric, prostate, ovarian, pancreatic, and colorectal cancer." (PMID 34919787, 2022). "For example, c-Myc and SOX9 were remarkably upregulated in the colorectal cancer and can accelerate cell proliferation." (PMID 34922552, 2021). "The expression of Cldn7 and Sox9 showed an opposite pattern in four colorectal cancer cell lines and the Cldn7 interference cell line." (PMID 34281572, 2021). "We applied this method for five biomarkers (CDX2, SOX2, SOX9, E-cadherin, and β-catenin) using tissue microarrays of a Norwegian unselected series of primary colorectal cancer." (PMID 31641225, 2020). "We performed DIA of fluorescence-based mIHC stains of CDX2, SOX2, SOX9, E-cadherin, and β-catenin in colorectal cancer samples arranged in TMAs, and compared with previous visually scored chromogenic IHC stains of the same series." (PMID 31641225, 2020). "It was stabilized by ubiquitin-specific protease 47 (USP47) which was regulated by transcription factor Sox9 in colorectal cancer cells under hypoxia." (PMID 32215176, 2020). "Conversely, the overexpression of SOX9 was reported to increase the tumourigenic potential of colorectal cancer cells grafted in nude mice." (PMID 31275454, 2019). "SOX9 knockdown resulted in decrease of proliferation and tumour growth capacity of colorectal cancer cells subcutaneously grafted or injected in the peritoneum of nude mice." (PMID 31275454, 2019). "To confirm efficacy of the SOX9 siRNAs, we selected the colorectal cancer cell line LS1034 for knockdown validation." (PMID 30683138, 2019). "SOX9 overexpression in colorectal cancer cells is sufficient to inhibit cell proliferation whereas SOX9 knockdown increases the proliferation of the human colorectal cancer cells." (PMID 31275454, 2019). "Conversely, in bladder and colorectal cancer, SOX9 participates in the progression of the disease, whereas it is correlated to metastasis in breast, gastric, pancreatic, and colorectal cancer." (PMID 31057614, 2019). "SOX9 was in a high expression in colorectal cancer compared with that of adjacent tissues (P < 0.01)." (PMID 30285605, 2018).